GPR32 (G protein-coupled receptor 32)
Description:
G protein-coupled receptor that binds to several ligands including resolvin D1 (RvD1) with high affinity, leading to rapid and transient activation of numerous intracellular signaling pathways. In macrophages, enhances the RvD1-stimulated phagocytic and clearance functions. Macrophages migrate less toward different chemoattractant stimuli but phagocytose more microbial particles. Prevents the increase in Ca(2+) and activation of ERK1/2 used by histamine and its H1 receptor subtype to induce goblet cell secretion by activating PKC and GRK2 to counter-regulate the histamine receptor.
Synonyms: RVDR1; DRV1
Tractability: Small molecule: it belongs to a druggable protein family. Antibody: its Gene Ontology location is reachable by antibodies, with high confidence; UniProt places it where antibodies can reach, with medium confidence; UniProt predicts a signal peptide or a membrane-spanning region.
Target class: Family A G protein-coupled receptor; Membrane receptor
Gene: Protein-coding gene on chromosome 19 (50,770,464 to 50,771,732, forward strand). Ensembl gene ENSG00000142511.
Subcellular location: Cell membrane
Pathways (Reactome):
Signal Transduction: G alpha (s) signalling events
Gene Ontology:
Molecular function: protein binding; complement receptor activity; G protein-coupled receptor activity; N-formyl peptide receptor activity
Biological process: complement receptor mediated signaling pathway; G protein-coupled receptor signaling pathway; inflammatory response; phospholipase C-activating G protein-coupled receptor signaling pathway; positive regulation of cytosolic calcium ion concentration
Cellular component: plasma membrane; membrane
Genetic constraint (gnomAD): Loss-of-function variants: 0 observed, 0.16 expected, observed/expected ratio (o/e) 0, 90% interval 0 to 1.88. That is too few expected variants to judge how well the gene tolerates losing a copy. Missense variants: 429 observed, 461.92 expected, observed/expected ratio (o/e) 0.93, 90% interval 0.86 to 1.01. Synonymous variants: 214 observed, 198.39 expected, observed/expected ratio (o/e) 1.08, 90% interval 0.96 to 1.21.
Homologues: Orthologues: chimpanzee GPR32 (99% identical), macaque GPR32 (89% identical), guinea pig GPR32 (49% identical). Paralogues in human: FPR2 (35% identical), FPR3 (32% identical), FPR1 (31% identical), CMKLR1 (30% identical), C3AR1 (28% identical), GPR33 (26% identical), C5AR1 (24% identical), C5AR2 (22% identical).
Diseases named in the same sentence as GPR32 in open-access papers:
GPR32 is named in the same sentence as 16 diseases in open-access papers, as found by Europe PMC text mining. Sharing a sentence is not in itself a finding about the gene and the disease. The quoted sentences say what the papers report.
gastric cancer (2 papers, 2022 to 2023). A primary or metastatic malignant neoplasm involving the stomach. "Genetic deletion of 15-lypoxygenase or of the RvD1 receptor GPR32 in gastric cancer cells led to an increase in the angiogenic and tumorigenic activities of those cells, therefore, demonstrating a protective role of those endogenous pathways involved in SPM production and action." (PMID 36903662, 2023).
periodontitis (2 papers, 2020 to 2021). An acute or chronic inflammatory process that affects the tissues that surround and support the teeth. "Previously, we demonstrated that the level of six lipid mediators (5-HETE, 15-HETE, 15(S)-HEPE, 4-HDHA, 7-HDHA, 17-HDHA) and expression of D-series resolvins corresponding receptor genes (GPR18, GPR32) were significantly altered by periodontitis treatment." (PMID 34177951, 2021). "The expression of GPR18 in periodontitis before treatment was significantly higher than in periodontitis after treatment while the expression of GPR32 in periodontitis before treatment was significantly lower than in periodontitis after treatment." (PMID 32670289, 2020). "After adjusting for BOP, expression of GPR32 gene in the periodontitis prior to treatment was significantly lower than in the periodontitis after treatment (p-value = 0.046) which was shown in the results of Wilcoxon signed rank test." (PMID 32670289, 2020). "It was found that expression of GPR18 (DRV2) gene was significantly higher in periodontitis subjects prior to nonsurgical therapy, while expression of GPR32 (DRV1) gene was significantly increased after nonsurgical therapy." (PMID 32670289, 2020). "The significantly increased expression of GPR32 gene after non-surgical therapy also suggests the role of D-series resolvins in resolution of inflammation in periodontitis." (PMID 32670289, 2020). "Furthermore, the expression of GPR18 gene was shown to be significantly higher in the periodontitis prior to SRP group compared to the periodontitis after SRP group (p-value = 0.04), while the expression of GPR32 gene showed the opposite pattern (p-value = 0.04)." (PMID 32670289, 2020).
amyotrophic lateral sclerosis (1 paper, 2025). Amyotrophic lateral sclerosis (ALS) is a neurodegenerative disease characterized by progressive muscular paralysis reflecting degeneration of motor neurons in the primary motor cortex, corticospinal tracts, brainstem and spinal cord. "Plasma resolvins were able to distinguish phenotypic variants of amyotrophic lateral sclerosis, and higher GPR32/GPR18 median expression was associated with longer survival." (PMID 39816195, 2025).
glioma (1 paper, 2022). A benign or malignant brain and spinal cord tumor that arises from glial cells (astrocytes, oligodendrocytes, ependymal cells). "On the other side, GPR32, another RvD receptor, proved to be a worse prognosis index in other cancers such as kidney chromophobe (KICH), cervical kidney renal papillary cell carcinoma (KIRP) and in low grade glioma (TCGA-LGG)." (PMID 35742918, 2022).
lung carcinoma (1 paper, 2020). "GPR32 is involved in the inhibition of TGF-β1-induced EMT by RvD1 in lung cancer cells and primary alveolar type II (ATII) cells." (PMID 33321955, 2020). "Additionally, GPR32 mediates the inhibition of epithelial mesenchymal transition (EMT) in lung cancer cell lines by RvD1." (PMID 33321955, 2020).
neurological diseases (1 paper, 2022). "RvD1 is most intensively studied RvDs, and exerts its potent anti-inflammatory and pro-resolving properties mediated through ALX/FPR2 or D resolving receptor 1 (DRV1/GPR32) in neurological diseases." (PMID 35865524, 2022).
tumor (1 paper, 2022). "The expression levels of the distinct genes of the RvD pathway ALOX15, ALOX15, FPR2, GPR18, GPR32, HPGD and PTGR1 were leveraged from 516 bulk tumor HNSC RNA-seq data, profiled by TCGA and plotted as a heatmap of individual tumor samples." (PMID 35742918, 2022).
GPR32 also shares sentences with these, for which no sentence is quoted: cancer (2 papers); Cardiovascular Disease (2); asthma (1); atherosclerosis (1); coronary artery disease (1); kidney chromophobe (1); peritonitis (1); Sepsis (1); Tremor (1).